CCND1 (cyclin D1)
Diseases named in the same sentence as CCND1 in open-access papers (continued):
Sharing a sentence is not in itself a finding about the gene and the disease.
breast cancer (continued). "In fact, alterations in the CCND1 gene or the p16Ink4a protein were neither in the phase II PALOMA-1 study, nor in the phase III PALOMA-2 trial predictors of better survival for breast cancer patients." (PMID 30959874, 2019). "Furthermore, expression of neither c-Myc, CCND1, nor LEF1 differed in TCGA breast cancer tumours with wild-type versus mutant RUNX1." (PMID 26916619, 2016). "Molecular biomarker HER2, but not CCND1 and TOP2A, may be a critical factor as a predictor of breast cancer prognosis." (PMID 25202398, 2014). "Actually, it is unknown whether TSC inhibits the expression of Cyclin D1 in an ERα-dependent manner because TSC repressed cell proliferation in both ERα-negative and ERα-positive breast cancer cell lines." (PMID 25101695, 2014). "Since APC has been shown to control the G1/S transition by regulating the β-catenin/TCF transcriptional targets c-myc and cyclin D1, these results suggest that APC suppression in these invasive breast cancer cells impacts neither β-catenin-mediated transcription nor proliferation." (PMID 23302090, 2013). "Another study found that the overexpression of MUC16 induces breast cancer cell proliferation via its interaction with the non-receptor tyrosine kinase JAK2, and this interaction mediates phosphorylation of transcription factor STAT3, which may transactivate c-Jun for Cyclin D1 expression." (PMID 39149564, 2024). "Thus, Lundberg and coworkers have explored the long-term prognostic and predictive capacity of cyclin D1 gene amplification in 2305 breast cancers, showing that a worse survival was observed for patients with luminal A and luminal B, ER+, lymph node-negative, HER2- breast cancers." (PMID 32210163, 2020). "Interestingly enough, the activity of CDK4 has been found not to strictly follow cyclin D1 expression in breast cancer cell lines, a finding suggesting that CDK4-independent functions of cyclin D1 may contribute to its biological effects as an oncogene in breast cancer." (PMID 28797035, 2017). "Wild-type PES1 promoted the expression of cyclin D1 in breast cancer cells, and the activation of cyclin D1 by PES1 was subject to regulation by SUMOylation, since the mutant PES1 that could not be SUMOylated had a weaker effect on the regulation of cyclin D1 expression." (PMID 27409667, 2016). "However, the expression levels of cyclin D1 and c-myc, but not those of Bcl-2 and Mcl-1, were increased upon PIAS3 overexpression in MCF7 cells, suggesting that the PIAS3-mediated effects on ER-positive breast cancer cells may be promoter-specific or ER-related." (PMID 26768588, 2016).
lung carcinoma (382 papers, 1997 to 2026). "There are reports underlining the role of cyclin D1 in the proliferation and invasiveness of lung cancer." (PMID 40301461, 2025). "This study aims to assess the relationship between a common polymorphism (rs9344 G > A) in CCND1 gene with cancer susceptibility, platinum-based chemotherapy response, toxicities and prognosis of patients with lung cancer." (PMID 38589850, 2024). "TBXT overexpression results in significant downregulation of p21, CCND1 (encoding cyclin D1), and phosphorylated Rb (p-Rb), which increases lung cancer resistance to radiotherapy and chemotherapy." (PMID 38965548, 2024). "We then conducted a meta-analysis to assess the association between CCND1 rs9344 and lung cancer susceptibility." (PMID 38589850, 2024). "The association between CCND1 A870G (rs9344) polymorphism and cancer risk has been previously investigated in lung cancer." (PMID 38589850, 2024). "This study aimed to investigate the association of CCND1 rs9344 with cancer susceptibility, platinum-based chemotherapy, toxicity and overall survival of patients with lung cancer by performing hospital-based case-control study." (PMID 38589850, 2024). "ARAP1-AS1 knockdown dramatically reduced lung cancer cell proliferation and clonogenicity and caused G0/G1 cell cycle arrest via reducing cyclin D1 expression." (PMID 37240281, 2023). "UA232 treatment of lung cancer cells caused the cells to arrest in the G0/G1 phase of the cell cycle in association with downregulation of cyclin D1 and CDK4." (PMID 36364289, 2022). "Consistently, we observed that CCND1 was drastically elevated in lung cancer tissues relative to adjacent tissues (by 3-fold), which was linked to the poor survival of patients with lung cancer." (PMID 35246017, 2022). "FZD9-/- adenomas had significantly higher expression of polo-like kinase 1 (PLK1) and cyclin D1, which are associated with altered cell cycle control in lung cancer." (PMID 35924166, 2022). "This study is the first to report an intriguing role of CAMSAP3 in lung carcinoma cell senescence‐associated phenotypes via the modulation of p‐ERK/cyclin D1 signaling." (PMID 34724356, 2021). "CCND1 (located on chromosome 1lql3, approximately 15 kB long), which encodes cyclin D, is a key driving gene for malignant transformation of lung cancer." (PMID 32148531, 2020). "For example, Kaiso can cause transcriptional repression of unmethylated Matrix Metallopeptidase 7 (MMP7) and Cyclin D1 (CCND1) genes as well as methylated Metastasis Associated 1 family member 2 (MTA2) gene in lung cancer." (PMID 31245293, 2019). "Cyclin D1 is frequently overexpressed in lung cancer patients and associated with poor survival of patients with lung cancer." (PMID 25760437, 2015). "The expression of cyclin D1, a cell-cycle regulator and a target gene of β-catenin, is increased in lung cancer and correlated with increased risk of tumor progression and metastasis." (PMID 26009991, 2015). "CCND1 G870A polymorphism was thought to affect cyclin D1 variant expression in nonsmall cell lung cancer, head and neck squamous cell carcinoma, and prostate cancer." (PMID 25851350, 2015). "For example, a coding synonymous SNP G870A of cyclin D1 (CCND1) with a modulating ability to its splice pattern was reported to be associated with lung cancer susceptibility." (PMID 23766705, 2013). "More recently studies in lung cancer cell lines have also implicated cyclin D1 as a Kaiso target gene." (PMID 23226276, 2012). "Effects of interactions between smoking and the CCND1 genotype on lung cancer risk have been suggested previously." (PMID 23170138, 2012). "This clinical activity was associated with reduced cyclin D1 expression in post-treatment lung cancer biopsies." (PMID 22923130, 2012). "The A-allele of the CCND1 870G>A (P242P) polymorphism, a proposed genetic risk factor for lung cancer, was previously associated with impaired cell cycle regulation and accumulation of DNA damage in the airway." (PMID 19750108, 2009).
lung carcinoma (continued). "Overexpression of CCND1 has been linked to tumor resistance to cisplatin in fibrosarcoma cell lines and in breast, pancreatic, colon and lung cancers." (PMID 16978399, 2006). "The minimal region of overlap observed on 11q (q13) is the site of the cyclin D1 gene which is an oncogene implicated in lung cancer." (PMID 14970871, 2004). "Finally, we analyzed the correlation between CCND1 rs9344 polymorphism and 5-year overall survival of lung cancer patients." (PMID 38589850, 2024). "In addition to the case-control study, a comprehensive meta-analysis for previous research on CCND1 rs9344 and lung cancer susceptibility was conducted." (PMID 38589850, 2024). "Additionally, a meta-analysis was conducted using 5432 cases and 6452 control samples to evaluate the association between CCND1 rs9344 polymorphism and lung cancer risk." (PMID 38589850, 2024). "This study conducted a hospital-based case-control investigation focusing on lung cancer, and systematically investigated the association between CCND1 rs9344 and lung cancer susceptibility, platinum-based chemotherapy sensitivity, toxicity, and overall survival." (PMID 38589850, 2024). "The relevance of cyclin D1 (CCND1) has been implicated in lung cancer progression." (PMID 35246017, 2022). "This sequence of post-replication events on Chromosome 11 led to loss of 50 Mb of the telomere end of 11q in a lung cancer and loss of 53 Mb of the same chromosome arm in an esophageal adenocarcinoma, combined in both cases with amplification of the CCND1 oncogene encoding cyclin D." (PMID 33802828, 2021). "In our previous study, by pharmacological exploration, we have found that tumor growth can be inhibited by cell cycle inhibition and antiangiogenesis with the VEGFA epidermal growth factor receptor CASP3 AKT1 CCND1 associated with the prognosis of lung cancer patients." (PMID 33628320, 2021). "In lung cancer, CCND1 mutation was significantly associated with pathological types and smoking." (PMID 34604069, 2021). "Loss of Cyclin K or Cyclin D1 markedly suppressed lung cancer cell growth and proliferation." (PMID 33042275, 2020). "Cyclin D1 is correlated with various tumor features, and the accumulation of cyclin D1 protein in the nucleus, detected by immunohistochemistry, is suggested as an adverse risk factor in various tumors, including prostate cancer and lung cancer." (PMID 30885146, 2019). "It was reported that claudin-2 could form a complex with zonula occludens (ZO-1), ZO-1-associated protein (ZONAB), and cyclin D1 leading to enhancement of cell proliferation, which contributed to the development of lung cancer." (PMID 28383479, 2017). "Moreover, loss of CCND1 expression also contributed to inhibition of lung cancer cell (both A549 and SPC-A-1 cells) growth and metastasis." (PMID 26840018, 2016). "Furthermore, TRIM24 overexpression was associated with high levels of cyclin D1 and p-Rb in lung cancer specimens." (PMID 22666376, 2012). "However, due to the limited number of studies and sample size, the exact role of CCND1 polymorphism in predicting lung cancer risk remains unclear." (PMID 38589850, 2024). "Thus, we hypothesize that the function of CCND1 in lung cancer cell proliferation and migration was associated with its transcription regulated by NF-κB." (PMID 35246017, 2022). "Impairment of NF-κB nuclear translocation with the recombinant peptide SN50 has been proved to attenuate the elevation in CCND1 expression caused by N-methyl-D-aspartate receptor agonist quinolinic acid in striatal neurons, which was largely in line with what we observed in lung cancer cells." (PMID 35246017, 2022). "CCND1 gene polymorphism (A870G) modulates alternative splicing and allows expression of an alternative cyclin D1 transcript (transcript cyclin D1b) which is correlated to the risk and/or severity of disease or drug response across a range of malignancies, including lung cancer." (PMID 30886859, 2019).
lung carcinoma (continued). "In lung cancer cells, depletion of eIF4H enhances sensitization to chemotherapy, decreases cell migration and inhibits tumor growth in vivo, in association with reduced translation of mRNA encoding cell-proliferation (c-Myc, cyclin D1) angiogenic (FGF-2) and anti-apoptotic factors (CIAP-1, BCL-xL)." (PMID 26498689, 2015). "Our study reveals that TIMM8A-TIMM13 complex, localized in the mitochondrial intermembrane space, drives lung cancer cell proliferation by upregulation of CCND1 and CDK6, thereby accelerating G1/S transition." (PMID 40918471, 2025). "In conclusion, this study demonstrates that components of the TIMM8A-TIMM13 complex exhibit elevated expression and potentially contribute to disease progression and poor outcomes in lung cancer patients through upregulation of CCND1 and CDK6." (PMID 40918471, 2025). "The mRNA transcripts of AKT1 and PTEN were upregulated (p < 0.05), while GSK3ß, CCND1 and P21 levels were downregulated (p < 0.05) in Odo A-treated lung cancer cells compared to the control group." (PMID 40141789, 2025). "In lung cancer, cyclin K stabilizes β-catenin and drives cyclin D1 expression, enhancing tumor proliferation and radioresistance." (PMID 40075638, 2025). "The present study indicates that ISO downregulates c-Myc and Cyclin D1 and suppresses the anchorage-independent growth of human lung cancer cells." (PMID 40362444, 2025). "AKT signaling has been shown to promote ZNF322A protein stability and transcriptional activity, which in turn positively regulates transcription of alpha-adducin (ADD1) and cyclin D1 (CCND1) to promote tumorigenicity in lung cancer." (PMID 40599863, 2025). "The Kaplan-Meier plot analysis also showed that lung cancer patients with high expression levels of CCND1 predicted lower overall survival (OS) and relapse-free survival (RFS)." (PMID 40770637, 2025). "A study demonstrated that hyperoside exerts an inhibitory effect on the lung cancer cell line A549, with its mechanism involving the suppression of cyclin D1 (CCND1) and cyclin-dependent kinase 4/6 (CDK4/CDK6) expression." (PMID 40098612, 2025). "Only few studies have been conducted to investigate the correlation between CCND1 rs9344 and platinum-based chemotherapy response in lung cancer." (PMID 38589850, 2024). "The prediction value of CCND1 rs9344 in the prognosis of lung cancer patients has been investigated in several previous studies." (PMID 38589850, 2024). "Exosome-mediated transfer of the selected microRNAs, including miR-130b-3p and miR-423-5p, to A549 lung cancer cells activated cyclin D1 signaling and increased the expression of phosphorylated p65, a cyclin D1 transcription factor." (PMID 39337604, 2024). "We also found that a combination of miR-130b-3p and miR-423-5p inhibitors not only inhibited cyclin D1 but also upregulated p21, leading to cell cycle arrest and the inhibition of lung cancer growth." (PMID 39337604, 2024). "CCND1 overexpression has been often observed with PTEN alterations in lung cancers suggesting SYN relationship." (PMID 39160568, 2024). "TPE-derived exosomes affect pathways that regulate the G1 to S transition in lung cancer, evidenced by an increase in cyclin D1 and a decrease in p21." (PMID 39337604, 2024). "The overexpression of CCND1 further promotes the development of lung cancer A549, leading to cell proliferation and inducing cell cycle arrest at the S phase." (PMID 38245694, 2024). "Intriguingly, in vitro results demonstrated a striking correlation with in silico examinations, showing decreased levels of NF-κB, Cyclin D1, p-AKT, and VEGF1 associated with significant promotion of lung cancer cell apoptosis." (PMID 39505930, 2024).
lung carcinoma (continued). "In non‐small cell lung cancer cells, Amentoflavone treatment significantly increases the cell population at the G1/G0 phase by decreasing the expression of cyclin D1, CDK4, and CDK6 in both H358 and H1299 cells." (PMID 38842135, 2024). "CPA4 knockdown has been reported to inhibit lung cancer cell proliferation by inducing cell cycle G1 arrest, downregulation of Cyclin D1 and apoptosis." (PMID 37162264, 2023). "BZN has been shown to induce p38 phosphorylation, thereby promoting p38-mediated degradation of cyclin D1 to repress lung cancer cells." (PMID 36765917, 2023). "MiR-34a-5p/miR-34c-5p/miR-302b-3p —LEF1—CCND1/WNT1/MYC axismay be a key mechanism in inhibition of lung cancer metastasis." (PMID 37191432, 2023). "It was further demonstrated that Cyclin D1 partially mediated the biological function of Cyclin K in lung cancer cells." (PMID 37626854, 2023). "Treating umbelliferone in lung cancer cells resulted in G1 phase arrest through decreasing expression of cyclin D1 but minimal change in cyclin E and A." (PMID 36597133, 2023). "Downregulation of TMPO-AS1 reduced lung cancer cells’ viability, increased cyclin D1 and BCL expression, and triggered apoptosis." (PMID 37240281, 2023). "Inhibition of PI3K/AKT pathway activity or suppression of NF-κB translocation in cells with high CCND1 expression was found to significantly reduce the activity of lung cancer cells in vitro and in vivo." (PMID 35246017, 2022). "In the present study, we set to dissect the possible upstream transcription factor of CCND1 in lung cancer." (PMID 35246017, 2022). "The correlation between CCND1 expression patterns and survival of lung cancer patients was analyzed using Cox multiple regression, and the results showed that high CCND1 expression was related to dismal prognosis of patients." (PMID 35246017, 2022). "Accordingly, MIA-602 and MIA-690 were previously found to inhibit the growth and progression of lung cancer by modulating the levels of cyclin D1, D2 and CDKs." (PMID 36232554, 2022). "The proposed mechanism is based on the androgen’s receptor induction of cyclin D1 expression, macrophage M2 polarization and direct effect on lung cancer growth." (PMID 35804979, 2022). "For GO functional annotation of the genes enriched in this pathway, we noticed that CCND1, which is known to be one of the key proteins in cell cycle regulation, was differentially expressed in lung cancer." (PMID 35246017, 2022). "In a recent study, miR-193a-3p mimic has been formulated in a novel lipid-based nanoparticle, named INT-1B3 which consistently suppresses some pro-tumorigenic phenotypes in lung cancer cell lines by downregulating the expression of oncogenic Cyclin D1." (PMID 36303933, 2022). "Meanwhile, ectopic expression of P65 also rescued S phase blockage and expression of cell cycle-related genes including CDK2, Cyclin D1 and Cyclin E1, in addition to NF-κB target genes including IL-1β, IL-6 and TNFα in lung cancer cells overexpressing ZNF24." (PMID 36457047, 2022). "Direct binding relationship between CCND1 and NF-κB in lung cancer was validated by immunofluorescence and ChIP assays in the current investigation." (PMID 35246017, 2022). "The gene expression of CCND1 between lung cancer and adjacent tissues examined by RT-qPCR revealed a 3-fold difference in mRNA expression." (PMID 35246017, 2022). "This miRNA was also reported to inhibit the growth and aggressiveness of human lung cancer through a FOXM1/cyclin D1/MMP2 axis." (PMID 35129056, 2022). "Ube1L expression is downregulated in lung cancer cells, and its upregulation attenuates lung cancer cell growth by inhibiting cyclin D1, which is essential for cell cycle progression." (PMID 36319753, 2022).